INS (insulin)
Diseases named in the same sentence as INS in open-access papers (continued):
Sharing a sentence is not in itself a finding about the gene and the disease.
Hypoglycemia (continued). "To investigate further the temporal profile of insulin-induced hypoglycemia of TRPC5 mutants and wild-type controls, we extended the observation period of the ITT from 60 to 150 min." (PMID 39375537, 2024). "When needed, participants receive education on insulin preparation, injection technique, site rotation, needle disposal, insulin storage, and hypoglycemia awareness and treatment." (PMID 38405028, 2024). "In terms of safety endpoints, the results showed significantly higher rates of level 1 hypoglycemia with once-weekly insulin (OR 1.42, 95% CI 1.26 to 1.60; I2 = 0%; p < 0.00001)." (PMID 39629047, 2024). "Correction is only needed for a hypoglycemia alert in symptomatic patients or within two to three hours of a bolus with an excess of active insulin, and usually a glucose dose of 0.1 g/kg is enough to raise glycemia above a safe level." (PMID 38894740, 2024). "Follow-up studies should also be done to evaluate patients’ adherence to medication, hypoglycaemia episodes and satisfaction with analogue insulin." (PMID 38694591, 2024). "The stomach plays a key, but often overlooked, role in the counterregulation of insulin-induced hypoglycemia because of a marked acceleration of gastric emptying, which increases the rate of carbohydrate absorption." (PMID 39568409, 2024). "Compared with placebo, GLP-1 RAs can significantly reduce body weight and basic insulin dosage, while DPP-4i and SGLT-2i have a lower risk of hypoglycemia." (PMID 39072050, 2024). "Limited research has been undertaken to explore how the timing of basal insulin injections impacts GV and hypoglycemia frequency." (PMID 39588847, 2024). "The investigators concluded that dasiglucagon safely and effectively prevented insulin-induced hypoglycemia and brought blood glucose levels up significantly faster than oral glucose." (PMID 39944479, 2024). "During the subsequent 1 year, the proband’s insulin requirement gradually decreased to as low as 0.3 unit/kg/day and he started developing multiple episodes of hypoglycemia, even with the low insulin dose." (PMID 39420905, 2024). "SF-1 gene expression in this nerve cell type was reduced in response to hypoglycemia; INS-injected animals exhibited further reductions in this mRNA profile as a consequence of SF-1 siRNA pretreatment." (PMID 39024550, 2024). "This treatment has been shown to lead to improved β-cell function and a decrease in hypoglycemia, which is a common side effect of insulin administration in stage 3 of T1D." (PMID 38097717, 2024). "Consistent with previous studies in patients hospitalized for hyperglycemic crises, hypoglycemia was more frequent in patients with low BMI, in patients with probable concomitant infection, and in those receiving higher doses of insulin." (PMID 38594758, 2024). "Across the trials, different combinations of SGLT2 inhibitors, DPP-4 inhibitors, metformin, and insulin were administered to evaluate their impact on glycemic control, cardiovascular and renal outcomes, weight changes, and hypoglycemia risks." (PMID 39723311, 2024). "Excess insulin administration resulting in severe hypoglycemia accounts for 6–10% of these fatalities." (PMID 39004753, 2024). "Insulin level at this time was 0.32 μIU/mL (1.92 pmol/L, normal range during hypoglycemia < 2 μIU/mL or < 12 pmol/L)." (PMID 39659385, 2024). "The insulin dosage was gradually decreased to prevent hypoglycemia, with the patient being discharged on 15 units before breakfast and 10 units before dinner of Insulin Degludec/Insulin Aspart Injection." (PMID 39575003, 2024). "Severe hypoglycemia was more frequent in the subjects who were treated with insulin and/or sulfonylureas, changed their dose of oral antidiabetic drugs or insulin, or modified their level of physical activity." (PMID 39203800, 2024). "Five out of 11 of the patients (45%) present with hypoglycemia were on gliclazide treatment, and four out of 11 (36.3%) were on insulin treatment." (PMID 39364503, 2024).
Hypoglycemia (continued). "If available, the use of CGM in people treated with insulin is recommended to optimize glycemic control and minimize hypoglycemia." (PMID 38559691, 2024). "Common medications such as metformin, insulin, repaglinide and sitagliptin can induce side effects like gastrointestinal disturbances, hypoglycemia, weight gain and specific organ risks." (PMID 38982323, 2024). "Our female patient showed subtle signs including mild hyponatremia, polyuria, and hypoglycemia despite conservative insulin doses which lead to further work-up and investigation." (PMID 38744309, 2024). "Elevated insulin levels restrict hepatic glucose mobilization and enhance muscle glucose disposal, potentially leading to hypoglycemia." (PMID 38542818, 2024). "Hypoglycaemia is a common medical emergency among diabetic individuals receiving insulin or sulfonylureas." (PMID 39651031, 2024). "It originates from the B cells of the pancreatic islets and produces insulin, so the diagnosis is prompted by symptoms of hypoglycemia, sometimes leading to neuroglycopenic symptoms (confusion, seizures, blurred vision, coma)." (PMID 39057179, 2024). "A third patient mistakenly injected 40 mg of semaglutide instead of insulin and had resolution of hypoglycemia within 24 hours after a dextrose bolus and feeding." (PMID 38861153, 2024). "Fears of insulin injection pain, concerns about insulin affecting daily life, costs of insulin treatment, problematic hypoglycemia, and misconceptions about insulin treatment are common reasons of the unwillingness to use insulin." (PMID 39036047, 2024). "The predictors included number of episodes of hypoglycemia-related utilization, insulin use, sulfonylurea (SU) use, prior year emergency room use, kidney disease, and age (c-statistic of 0.83)." (PMID 38607977, 2024). "This indicates that the use of the sensor is effective in reducing hypoglycemia in insulin-dependent patients." (PMID 38541647, 2024). "Regarding the geographical region, random interactions resulting from the imbalance in the number of studies in particular subgroups were noticed for unexplained hypoglycemia and the total daily insulin dose." (PMID 38215209, 2024). "Because of severe BS fluctuations accompanying fasting hypoglycemia, we reduced the insulin dose to 0.3 unit.kg−1 per day." (PMID 38923174, 2024). "For example, in hypoglycemia induced by self-injection of insulin, laboratory analysis will show a triad of hypoglycemia, high immunoreactive insulin and normal or suppressed plasma C‐peptide immunoreactivity." (PMID 38376552, 2024). "Real-world population-based studies showed a high incidence of nocturnal hypoglycemia, with reported rates of 2.6–11.3 events per patient-year in insulin-treated subjects with type 1 diabetes (T1D)." (PMID 38611653, 2024). "The HFF control group reached hypoglycemia much faster than the T2D rats following bolus insulin administration to induce hypoglycemia in both the vehicle- and SSTR2 antagonist-treated (PRL-2903) conditions." (PMID 38510652, 2024). "PSHI is an exaggerated form of transitional hypoglycemia triggered by hypoxia-mediated reduction of the beta-cell glucose threshold for suppression of insulin secretion." (PMID 37454648, 2024). "Currently, the importance of somatostatin secreted by delta cells is discussed with respect to insulin-induced hypoglycemia in diabetic models." (PMID 38228886, 2024). "This study indicates that reduced insulin levels coupled with hypoglycemia strongly suggest a diagnosis of NICTH as a paraneoplastic syndrome associated with GIST." (PMID 39219869, 2024). "The study investigated aspects such as insulin administration, hypoglycemia management, and the use of glucagon." (PMID 39195172, 2024). "Insulin is the first-line treatment in T1DM but is associated with weight gain, increased glycemic variability, and hypoglycemia." (PMID 38962634, 2024).
Hypoglycemia (continued). "IGlar can be prescribed only for type-1 diabetes (T1D) under the conditions that patients have severe hypoglycemia or nocturnal hypoglycemia after using multiple daily human insulin injections." (PMID 39877917, 2024). "Many hospitals still use sliding-scale insulin regimens despite their ineffectiveness in achieving adequate in-hospital glucose control, possibly out of fear of hypoglycaemia." (PMID 39099754, 2024). "Overall level 2 (<54 mg/dL) hypoglycemia rates were low (<1 event per PYE) in allof these studies in insulin-naive patients." (PMID 38224978, 2024). "Medical management of hypoglycemia includes frequent glucose administration, diazoxide to inhibit insulin release, octreotide to suppress hormone secretion, and corticosteroids to antagonize insulin action." (PMID 39677258, 2024). "While insulin therapy is still the most effective treatment option for T1D, new drugs are desperately needed to address some of its drawbacks, including hypoglycemia and weight gain." (PMID 39273299, 2024). "In fact, fear of hypoglycemia and hypoglycemia events have a large impact on patient quality of life, and constitute a major obstacle for optimization of insulin therapy." (PMID 38982528, 2024). "The aim of this project was two-fold: firstly, to assess the incidence of hypoglycaemia in hospitalised patients with renal disease following acute treatment of hyperkalaemia with insulin and dextrose." (PMID 38871123, 2024). "HH is characterised by hypoglycaemia with an inadequate suppression of insulin, detectable C-peptide, a suppressed or low level of ketones (3-β-hydroxybutyrate < 2 mmol/L) and an absence of metabolic acidosis." (PMID 38397245, 2024). "According to the literature, administration of 10% sucrose water is intended to rescue animals from fatal hypoglycemia during the initial STZ injection, which is associated with the uncontrolled release of insulin from dying β‐cells." (PMID 39350510, 2024). "Interventions with liraglutide decreased HbA1c, daily insulin dosage, and body weight in patients with T1DM, according to the ADJUNCT studies; however, the risk of hypoglycemia and ketosis was also raised." (PMID 39768947, 2024). "Historically, self-monitored blood glucose (SMBG) was crucial in the prevention of hypoglycemia during intensified insulin therapy." (PMID 38397994, 2024). "Studies on mice revealed the presence of V1bR mRNA at the pancreatic α-cells and showed that enhanced release of AVP and stimulation of V1bR play a significant role in the elevation of glucagon release during insulin-mediated hypoglycemia." (PMID 39769071, 2024). "The decrease in catecholamines after pheochromocytoma removal induces a decline in gluconeogenesis and a relative increase in insulin secretion, resulting in hypoglycemia." (PMID 39498182, 2024). "Due to the patient’s clinical findings of hypoglycemia, evidence of overproduction of endogenous insulin, and confirmation of tissue biopsy, the diagnosis of insulinoma was concluded." (PMID 39156287, 2024). "On the other hand, exercise-related hypoglycemia is a major concern of people with diabetes; primarily those on insulin treatment." (PMID 39171092, 2024). "The risks of human insulin include weight gain, recurrent hypoglycemia (severe hypoglycemia as well as mild, ‘silent’ hypoglycemic episodes), and iatrogenic hyperinsulinemia, among other adverse effects." (PMID 38933821, 2024). "We removed individuals from the study population who were using insulin and/or sulfonylureas or had documented hypoglycemia events during baseline." (PMID 39093563, 2024). "It does not appear that oxidative stress plays a central role in neuronal damage following severe insulin-induced hypoglycemia." (PMID 39004753, 2024). "This association is consistent with extensive literature suggesting that hypoglycemia risks are pronounced with insulin therapy, both basal insulin and intensive strategies, sulfonylurea, and glinide." (PMID 38429847, 2024).
Hypoglycemia (continued). "Strikingly, insulin-induced hypoglycemia resulted in significantly smaller elevations of plasma glucagon levels in α-GsKO mice, probably partially due to the reduction in pancreatic glucagon content caused by α-cell Gαs deficiency." (PMID 38879678, 2024). "In patients with CFRD, the residual endogenous insulin production alongside increased insulin delivered by the insulin pump can lead to reactive post-prandial hypoglycemia." (PMID 38966218, 2024). "It is worth emphasizing that after SB, the insulin on board (IOB) level is high, which increases the risk of hypoglycemia." (PMID 38257156, 2024). "A single episode of insulin-induced hypoglycaemia significantly increases plasma adrenaline levels in diabetic and non-diabetic rats and humans (see review)." (PMID 38392992, 2024). "1st generation non-selective betablockers block both β1 and β2 receptors, thus decreasing insulin secretion, glycolysis and lipolysis, while increasing glycogenolysis and gluconeogenesis and are prone to mask the symptoms of hypoglycemia." (PMID 39140033, 2024). "Antecedent hypoglycemia (blood glucose 2.8 mmol/L) does not appear to attenuate the acceleration of gastric emptying by subsequent insulin-induced hypoglycemia in health." (PMID 39568409, 2024). "Simultaneously, insulin and glucagon blood concentrations in dogs with hypoglycemia preoperatively and postoperatively were compared to verify the physiological responses to hypoglycemia." (PMID 38393097, 2024). "Plasma glucagon increased within the first hour following ZT-01 treatment compared to controls, and remained elevated until 1 h after insulin bolus administration for hypoglycemia induction (2 h after ZT-01 dosing)." (PMID 38510652, 2024). "High-fat-diet fed and low-dose streptozocin-treated C57BL/6N mice were exposed to one (acute hypoglycaemia [AH]) or multiple (recurrent hypoglycaemia [RH]) insulin-induced hypoglycaemic episodes and plasma glucagon levels were measured." (PMID 38017352, 2024). "Our research has also revealed that dapagliflozin treatment in female mice exerts a preventive effect against hypoglycemia induced by insulin." (PMID 39906039, 2024). "Reduced reliance on sulfonylureas or human insulin, and preferential use of alternate approaches and pharmacotherapies, can successfully avoid much of the hypoglycemia with antidiabetes management in the past." (PMID 38933821, 2024). "Hypoglycemia occurred more in patients who were on premix insulin 26(45%) than those on basal bolus 20(41.7%) and basal only 2(4.2%)." (PMID 38827884, 2024). "An important and persistent finding was glycosuria even in the presence of patient hypoglycemia during insulin therapy." (PMID 38923174, 2024). "Throughout her stay, she was noted to have frequent episodes of hypoglycemia, particularly in the early morning hours, despite a conservative insulin dose." (PMID 38744309, 2024). "Among these cases, six patients who were receiving treatment with sulfonylureas or insulin experienced symptomatic hypoglycemia." (PMID 39834467, 2024). "Starvation experiments are illegal and real hypoglycemia (also insulin induced) would initially introduce physiological responses (gluconeogenesis, ketogenesis) that interfere with and mask the paradigm itself." (PMID 39251890, 2024). "Accelerated gastric emptying with rapid increases in glucose and AA absorption, together with elevations in GLP-1 and other intestinally derived hormones, contributes to increased postprandial insulin secretion and subsequent hypoglycemia." (PMID 39264731, 2024). "In studies focusing on antidiabetic medications, insulin and sulfonylureas were identified as significant contributors to hypoglycaemia-related hospitalisations or ED visits." (PMID 38256662, 2024). "When treating sulfonylurea-induced hypoglycemia, octreotide is the primary treatment of choice because it prevents insulin secretion and maintains euglycemia when combined with dextrose." (PMID 39347364, 2024).
Hypoglycemia (continued). "IAS should be considered as a differential diagnosis even in patients presenting with fasting hypoglycemia, and this case report sheds light on the link between the common over-the-counter drug omeprazole and insulin autoantibody syndrome." (PMID 38926797, 2024). "Despite the decrease in catalase activity in the brain, the total antioxidant capacity following severe insulin-induced hypoglycemia increased." (PMID 39004753, 2024). "The AI: GR corrected insulin/glucose ratio can be applied in the investigation of patients with hypoglycemia, even though its use for insulinoma diagnoses is questionable." (PMID 38539988, 2024). "Although sex differences were beyond the scope of this study, additional studies will be conducted as a follow-up to assess any differences in insulin sensitivity and subsequent efficacy of ZT-01 for hypoglycemia prevention in female animals with T2D." (PMID 38510652, 2024). "Recent advancements in insulin formulations and delivery methods, such as ultra-rapid-acting analogs and inhaled insulin, offer potential benefits in terms of reducing hypoglycemia and improving glycemic control." (PMID 39065795, 2024). "Hypoglycemia (<70 mg/dL) during IV insulin administration was higher in the Early group than in the Late group (27% vs. 19%, p = 0.042)." (PMID 39136541, 2024). "A growing body of evidence supports screening for IGF‐2 in non‐diabetic persons with hypoglycaemia and suppressed insulin and c‐peptide levels." (PMID 38411039, 2024). "For older patients using automated insulin delivery systems, prioritizing the reduction of TBR is recommended to decrease the risk of hypoglycemia." (PMID 38571669, 2024). "Persistent congenital hyperinsulinism (HI) is a rare genetically heterogeneous condition characterised by dysregulated insulin secretion leading to life-threatening hypoglycaemia." (PMID 38605124, 2024). "Once‐weekly insulin icodec or basal insulin Fc (insulin efsitora α) has been reported to provide better or similar glycemic control compared with a once‐daily basal insulin analog, and the rate of hypoglycemia is similar or lower." (PMID 39375857, 2024). "The Warburg Therapy uses insulin to induce hypoglycemia to create a low blood glucose window in which a combination of the chemotherapy drugs fluorouracil and cyclophosphamide are administered." (PMID 39629677, 2024). "In humans, a significant impact of insulin-induced hypoglycemia on AVP secretion has been documented in multiple studies using estimations of plasma copeptin level, as a surrogate marker of vasopressin secretion." (PMID 39769071, 2024). "While four patients developed hypoglycemia, two of these patients co-administered large doses of a long-acting insulin." (PMID 38861153, 2024). "Due to hypoglycaemia (2.0∼3.0 mmol/L) and frequent drowsiness, insulin was changed to glibenclamide (0.06 mg/kg/d) at the age of three months, which was discontinued after the genetic diagnosis at the age of 20 months." (PMID 38365697, 2024). "The incidence of symptomatic hypoglycemia is estimated to be one to two episodes per week per person in T1D, whereas in individuals with type 2 diabetes (T2D) using insulin or sulfonylureas, it is estimated to be 0.4 episodes per week per person." (PMID 38323079, 2024). "The drawbacks of insulin treatment include invasive administration along with risks of hypoglycemia and weight gain." (PMID 38258903, 2024). "During the first observation period, 34% (42/124) of insulin/dextrose treatments resulted in hypoglycaemia, of whom 17/42 developed severe hypoglycaemia." (PMID 38871123, 2024). "Dumping syndrome, where food moves rapidly from the stomach to the small intestine, often induces an exaggerated insulin response and hypoglycemia during an OGTT." (PMID 38753665, 2024).